STAT3 (signal transducer and activator of transcription 3)
Diseases named in the same sentence as STAT3 in open-access papers (continued):
Sharing a sentence is not in itself a finding about the gene and the disease.
cancer (continued). "Notably, IL-6/STAT3 conditioned monocyte-derived DC (MoDC) showed an incomplete ability to induce cancer-related cytokines production by antigen-specific Th cells." (PMID 33584695, 2020). "The NTD is part of the dimerization surface in STAT3 and is important for efficient nuclear accumulation, DNA binding, and regulation of gene expression, including the regulation of proapoptotic gene expression in cancer cells." (PMID 33318172, 2020). "Consequently, alternative or complimentary therapies targeting STAT3 signalling in metabolically flexible cancers would be beneficial." (PMID 32731620, 2020). "As a result, testing FDA-approved drugs may help us find potential inhibitors of STAT3 and promote its quick translation into clinic to treat human cancers." (PMID 32733808, 2020). "Innovative inhibitors of STAT3 would provide novel strategies for treating human cancers." (PMID 32489321, 2020). "As a transcription factor in cytoplasmic, STAT3 could be activated in the cell signaling cascade in various cancers and acts as an important component in both EMT process and metastasis." (PMID 32934214, 2020). "Further, the outstanding performance of SD-36 in cancer treatment suggests that the strategy of targeting STAT3 protein degradation may be superior to suppress STAT3 expression." (PMID 32972405, 2020). "STAT3 regulates the expression of essential genes that mediate cancer progression." (PMID 32273843, 2020). "Importantly, due to the proven role of EMT in cancer progression, STAT3 inhibitors represent yet another group of promising candidates for cancer treatment in combination with radiotherapy." (PMID 33322336, 2020). "In a recent study, cucurbitacin I (CUI) has been identified as a strong inhibitor of the JAK2/STAT3 signaling pathway (a common oncogenic signaling pathway), which is constitutively activated in many types of cancer; hence, it is considered as a milestone in cancer therapy." (PMID 32034276, 2020). "Furthermore, our previous report suggests that SH003 inhibits STAT3 activation and induces cell death in cancer cells." (PMID 32879309, 2020). "Indeed, CDK7 was found to be associated with the important transcription factor MYC and with the STAT3 and β-catenin pathways which play crucial roles in tamoxifen resistance, stemness, and cancer progression." (PMID 32340192, 2020). "Finally, we will discuss CD44 and STAT3 involvement in cancer-driven metabolism switches and summarize currently available data on CD44 therapeutic targeting alone or in combination with STAT3, highlighting promising therapeutic opportunities for the future." (PMID 33335857, 2020). "The STAT3 signaling pathway has been demonstrated to be important for cancer progression." (PMID 33267888, 2020). "In addition, cancer cell-derived G- and GM-CSF act via STAT3/5 in a paracrine manner on infiltrating MDSCs, to upregulate the expression of CD36 receptor and enhance the uptake of exogenous fatty acids." (PMID 32823961, 2020). "As a result, we assume that mitochondrial STAT3 may be a potential target in enhancing the radioresensitizing effect of cancer cells." (PMID 32733808, 2020). "The mRNA expression levels of STAT3 were explored by TIMER in many cancer types." (PMID 32486001, 2020). "In addition, STAT3 has various effects on cancer cell activity, such as angiogenesis, metastasis, and inhibition of cancer cell apoptosis." (PMID 33351844, 2020). "Therefore, the suppression of the STAT3 signal transduction pathway has been investigated as a cancer therapeutic strategy." (PMID 32150979, 2020). "This review highlights the new findings about STAT3 in cancer metabolism." (PMID 33003453, 2020). "Interestingly, the observed effect was abolished by the monoclonal antibody tocilizumab against the IL-6-receptor, highlighting the IL-6/JAK/STAT3 pathway as a possible therapeutic target in cancer." (PMID 32528731, 2020).
cancer (continued). "The findings of the current study support the notion that the anti‐cancer effect of HJC0152 against NSCLC may be primarily mediated by STAT3 signalling, a key regulator of cellular metabolism and ROS production." (PMID 32022328, 2020). "In addition, depletion of OBR inhibited the leptin-induced accumulation of p-STAT3 in the nucleus of cancer cells." (PMID 33371368, 2020). "Beyond phosphorylation, other posttranslational modifications (i.e. acetylation, methylation, and sumoylation) can also regulate STAT3 transcriptional activity through altering STAT3 phosphorylation, and thus add another layer of complexity for STAT3 hyperphosphorylation in cancers." (PMID 32972405, 2020). "Oligonucleotides represent a new treatment strategy for ‘undruggable’ cancer targets such as STAT3." (PMID 32972405, 2020). "In addition to these Bcl-2 family proteins, persistently altered STAT3 activity is known to promote the proliferation and survival of cancer cells via regulation of apoptosis." (PMID 32722030, 2020). "Such peroxide increases may lead to the transfer of the oxidative equivalents to STAT3 or other proteins, initiating redox signaling events that result in the inhibition of cancer cell proliferation." (PMID 32264893, 2020). "Furthermore, Ras-induced Prx II enhances the self-renewal properties of cancer cells through the activation of VEGFR2/STAT3 signaling in HCC." (PMID 31952344, 2020). "Interrupting the STAT3 pathway by using STAT3 inhibitors, RNA interference and short hairpin RNA could sensitize radioresistant cancer cells and improve clinical outcomes." (PMID 32872659, 2020). "Moreover, STAT3/Rabs-mediated exosome release was correlated with a more aggressive and chemoresistant cancer phenotype under hypoxic conditions and a recent study demonstrated a role for Rab18 in resistance to cisplatin-induced apoptosis." (PMID 32823947, 2020). "IPA analysis of the differentially expressed genes showed significant downregulation of a number of pathways involved in cancer progression, including cellular migration and invasion, integrin signaling (integrin β3), STAT3 and growth factor signaling (HGF, PDGF, and IGF)." (PMID 32352029, 2020). "Seemingly, there is substantial crosstalk between the NFKB and STAT3 pathways in cancer." (PMID 32331320, 2020). "Interestingly, it has been reported that MDSCs can regulate the biology of cancer stem cells by affecting the IL-6/STAT3 and NO/NOTCH signaling pathways." (PMID 32005273, 2020). "Moreover, STAT3-induced Akt phosphorylation triggers the expression of PKM2 in cancer cells, which also explains our findings." (PMID 31819176, 2020). "Interestingly, our results revealed that VX-680 and GSK-J4 showed a positive response to STAT3 in cancer." (PMID 32486001, 2020). "Therefore, additional studies are required to elucidate the cell-autonomous functions of STAT3 in Treg cells and other immune cells during cancer." (PMID 33143070, 2020). "Thus, STAT3 target genes in cancer can be expressed very efficiently both at the transcription level and at the translation level." (PMID 32495998, 2020). "Moreover, several lncRNAs have been shown to be involved in Wnt/β‐catenin and STAT3 signaling, cancer stem cells, and epithelial‐to‐mesenchymal transition in HCC." (PMID 32525601, 2020). "Inhibition of STAT3/JAK2 pathway has been formerly proved to induce apoptosis in cancer cells." (PMID 33680016, 2020).
cancer (continued). "Four STAT3 over-activated human cancer cell lines (i.e., human breast carcinoma MDA-MB-231 and MCF-7 cells, human colonic carcinoma HCT-116 cells and human hepatocellular carcinoma HepG2 cells) were selected to assess the biological activity of the newly-synthesized compounds." (PMID 32610556, 2020). "Thus, we have uncovered a mechanism in which ID1 confers cancer cell chemoresistance largely through the STAT3/ATF6-induced autophagy." (PMID 32080166, 2020). "Furthermore, STAT3-regulated lipid metabolism is critical for cancer stem cell self-renewal and therapy resistance." (PMID 32731620, 2020). "Moreover, we also summarized the ratio of patients (maximum 12 patients) with the high and medium levels of STAT3 in 20 cancer tissues." (PMID 32486001, 2020). "In addition, STAT1 and STAT3 have different roles in cell apoptosis and the progression of malignant tumors." (PMID 33361763, 2020). "Pin1 has been reported to enhance the IL‐6/STAT3 pathway in different cancer types." (PMID 32347623, 2020). "STAT3 is, therefore, a legitimate target for cancer management and therapy." (PMID 32182833, 2020). "After treatment with a STAT3 inhibitor, cancer cells were sensitized to chemotherapeutic drugs." (PMID 32477122, 2020). "Additionally, cancer cell expression of PD-L1 protects against IFN cytotoxicity through inhibition of signal transducer and activator of transcription 3 (STAT3) phosphorylation, an important transcription factor in the IFN signal transduction pathway." (PMID 32111080, 2020). "In our study, after screening a group of biomarkers which may have potential field effects, we found that the immunoreactivity of p‐STAT3, Mcm2 + and/or MSR1 were associated with cancer and HGPCa at repeat biopsy." (PMID 32860339, 2020). "Then, a detailed analysis is needed to reveal the correlation between STAT3 and compounds in different cancer types, and it may provide a better understanding of STAT3 in cancer therapy." (PMID 32486001, 2020). "Using small molecule inhibitors targeting these proteins, we confirmed dose and time dependent inhibition of STAT3-mediated transcription, suggesting that inhibition of these kinases may provide strategies for dampening STAT3 activity in cancers." (PMID 32231398, 2020). "Consistently, STAT3 positively related to DC infiltration in cancer." (PMID 32486001, 2020). "We revealed that PKM2, eEF2K and STAT3 formed a complex and that STAT3 phosphorylation was correlated with expression of c-Myc, a well-known STAT3 target gene and a key contributor to the Warburg effect in most cancer types, leads to both increased aerobic glycolysis and proliferation." (PMID 32054489, 2020). "In recent years, STAT3 has become an emerging target in cancer treatment." (PMID 32869923, 2020). "However, while IL‐6 is pro‐tumorigenic supporting cellular proliferation, metastases and survival through mechanisms including activation of the JAK/STAT3 signaling pathways, high levels have been reported to be a poor prognostic marker in cancer." (PMID 32383556, 2020). "The expression level of p-STAT3 could reflect the activity in cancer progression better than total STAT3 protein expression." (PMID 32486001, 2020). "As such, the inhibition of STAT3 and STAT5 may offer a therapeutic benefit in HPV-associated cancers." (PMID 32899142, 2020). "However, AG490 can effectively block the activation of the JAK2/STAT3 signaling pathway in different cancer cell lines 28,31." (PMID 33123268, 2020). "As with STAT3, activation of EGFR signalling may induce STAT5 phosphorylation in HPV-associated cancers." (PMID 32899142, 2020). "Moreover, additive growth factors for tumorsphere formation, such as EGF and IL6, can phosphorylate STAT3 in cancer cells." (PMID 33023006, 2020). "STAT3 has proved to be a promising molecule target in treating cancers." (PMID 32422984, 2020).
cancer (continued). "It has been reported that NF-κB and STAT3 cooperate to promote the development and progression of gastric, colon, and liver cancers, which contribute to explain the molecular pathogenesis of cancers, and offer opportunities for the design of new therapeutic interventions." (PMID 33041664, 2020). "In addition, C48, a selective STAT3 inhibitor, alkylates Cys468, present in the DNA-binding interface, then blocks the accumulation of activated STAT3 in various cancer cells." (PMID 33003453, 2020). "Interestingly, as observed in the CD45+ population in cancer biopsies, in PBMCs from cancer patients, there was a positive correlation between Akt and STAT3 and CREB expression." (PMID 33330068, 2020). "Notably, there are previous studies illustrating that 6-Shogaol suppresses the phosphorylation of STAT-3, which partially mediates its antiproliferative and proapoptotic effects on certain cancer cells." (PMID 32998376, 2020). "Understanding the mechanisms of STAT-3 activation and transcriptional events from thereceptor on cell surface to the nucleus may provide different approaches to targetSTAT-3 in cancer therapeutics." (PMID 32167126, 2020). "However, despite major roles for STAT3 in human health, including in cancers, the signalling profiles and biological roles of specific STAT3 dimers remains poorly understood." (PMID 32903273, 2020). "Activation of STAT3 has been found more often than STAT5 or any other STATs in cancers." (PMID 32087696, 2020). "A previous report showed that CPA4 activated STAT3 in cancer cells." (PMID 32347291, 2020). "Stat3 was expressed highly in the cytoplasm and nucleus of cancer cells." (PMID 32281236, 2020). "In addition, TRIB3 is necessary for EGF-induced STAT3/5 activation, which is critical for cancer stemness and chemoresistance." (PMID 32694521, 2020). "In this context, we also evaluated if a modulation of STAT3 activation could mediate the chemosensitizing and chemopreventive effects of β-caryophyllene in normal and cancer cholangiocytes." (PMID 32252311, 2020). "In cancer cells, IL-6 functions as an upstream mediator of STAT3 signaling pathway." (PMID 32545648, 2020). "Moreover, STAT3 signaling plays a pivotal role in the conversion of monocytes into functional MDSCs in cancer setting." (PMID 33584695, 2020). "Among the potential interacting proteins, we focused on STAT3 in the subsequent studies, due to the fact that STAT3 has been proved to play critical roles in driving the proliferation, invasiveness, and metastasis of cancer cells." (PMID 32123532, 2020). "To further investigate the potential mechanism of phytochemical approaches to cancer treatment, we summarized the correlation between transcriptional expression level of STAT3 and sensitivity to natural compounds in cancer cell lines by CCLE and CTRP databases." (PMID 32486001, 2020). "Targeting STAT3 orchestrated lipid metabolism has shown therapeutic promise in human cancer models." (PMID 32731620, 2020). "In addition to its established role as an oncogene in cancer, STAT3 regulates mitochondrion functions and gene expression through epigenetic mechanisms." (PMID 33361763, 2020). "Moreover, IL-6 activates STAT3 and NF-κB by (i) autocrine and paracrine signaling and (ii) via synergistic crosstalk between the pathways in BC cells, resulting in cancer cell proliferation and apoptosis evasion." (PMID 31963198, 2020). "Constitutive activation of STAT3 in cancers results from activation of several oncogenic pathways." (PMID 32422984, 2020). "JAK2/STAT3 pathway is frequently upregulated in many human cancers." (PMID 33123268, 2020). "We suggest that the STAT3/mLST8/4E‐BP1 signal pathway might be a valuable target for cancer therapy." (PMID 32495998, 2020). "MET, EGFR and STAT3 function as oncogenes in many types of malignant tumors including NSCLC." (PMID 33318313, 2020).
cancer (continued). "Besides, G-protein alpha-subunit (GNAS) as an upstream mediator can induce the STAT3 signaling pathway through IL-6 to enhance the malignancy and proliferation of cancer cells." (PMID 32380783, 2020). "STAT3 is one of the most important transcription factors in the growth of cells, regulating cell proliferation and apoptosis, and is continuously activated in human cancer cells." (PMID 32071920, 2020). "Moreover, the association between STAT3 and drug response was evaluated by the Cancer Cell Line Encyclopedia (CCLE) and Cancer Therapeutics Response Portal (CTRP)." (PMID 32486001, 2020). "These endeavors provide new insights into the translational application of STAT3 in cancer and may contribute to the promotion of more effective treatments toward malignancies." (PMID 32972405, 2020). "Importantly, Niclosamide has been confirmed to target the Wnt/β-catenin, mTOR, STAT3, NF-κB, and Notch pathways has been widely investigated in multiple cancer types." (PMID 32284741, 2020). "Additionally, cancer-associated adipocytes form a proinflammatory microenvironment via induced macrophage invasion and thus synergistically activate STAT3 and NF-κB pathways, which in turn leads to apoptosis inhibition and cancer cell proliferation." (PMID 31963198, 2020). "Conversely, inhibition of STAT3 reduces muscle atrophy in cancer." (PMID 31941005, 2020). "Additionally, STAT3 expression is tightly correlated with specified inhibitors and natural compounds treatment response in cancer." (PMID 32486001, 2020). "Moreover, miR‐500a‐3p promotes cancer stem cell characteristics by activating the JAK/STAT3 signaling pathway." (PMID 32961635, 2020). "We also evaluated STAT3 signaling because of its reported role in cancer drug resistance." (PMID 32901049, 2020). "This anticancer effect is associated with the downregulation of cancer stemness and EMT, which could be related to the suppression of STAT3 and NOTCH signaling pathways." (PMID 33091036, 2020). "The JAK/STAT3 signaling pathway plays an essential role in various types of cancers." (PMID 31952344, 2020). "STAT3 activation directly regulates the expression of oncogenes and promotes the suppression of anticancer immune responses, which facilitates the expansion of cancer." (PMID 32488850, 2020). "Particularly, STAT3 activation promotes EMT of cancer cells." (PMID 32984052, 2020). "Consistent with our data, STAT3 was involved in the PI3K signaling pathway in cancer." (PMID 32486001, 2020). "Downregulation of Mcl-1 transcription by inhibiting STAT3 cascade may be a potential strategy for the treatment of this cancer." (PMID 31956373, 2020). "It is worth mentioning that, in addition to chemoresistance, the STAT3 signaling pathway may trigger the immune evasion of cancer cells." (PMID 32545648, 2020). "Both epigenetic suppression of SOCS3 and the paracrine signals in the TME may contribute to the sustaining stimulus for STAT-3 activation in multiple forms of cancer." (PMID 32855767, 2020). "Thus, the lncRNA PTCSC3 regulates the pathogenesis of ATC by modulating STAT3 signalling and CSCs phenotype of cancer cells." (PMID 33126409, 2020). "STAT3 signaling is constitutively activated in various cancer types." (PMID 32351887, 2020). "Strikingly, a phase Ib/II study showed that napabucasin, a first-in-class cancer stemness inhibitor that targets the STAT3 pathway, when given with weekly paclitaxel treatments, has shown promising effects in metastatic TNBC patients who have progressed on taxane-based treatment regimens." (PMID 32391382, 2020). "Furthermore, for the first time, it was found that the addition of sclareol to cyclophosphamide treatment increased the potency of this anti-cancer agent via the induction of apoptotic cell death as well as inhibition of STAT3 phosphorylation." (PMID 32922496, 2020). "Furthermore, an increasing number of studies suggest that STAT3 plays a crucial role in the regulation of anoikis resistance and invasion of cancer cells." (PMID 32326395, 2020).